SNAPC1 (small nuclear RNA activating complex polypeptide 1)
Description:
Part of the SNAPc complex required for the transcription of both RNA polymerase II and III small-nuclear RNA genes. Binds to the proximal sequence element (PSE), a non-TATA-box basal promoter element common to these 2 types of genes. Recruits TBP and BRF2 to the U6 snRNA TATA box.
Synonyms: SNAP43; PTFgamma
Tractability: Small molecule: a structure with a bound ligand is known. PROTAC: ubiquitination databases record sites on it.
Gene: Protein-coding gene on chromosome 14 (61,762,325 to 61,796,443, forward strand). Ensembl gene ENSG00000023608.
Subcellular location: Nucleus
Subcellular location (Human Protein Atlas): Nucleoli; Nucleoplasm
Pathways (Reactome):
Gene expression (Transcription): RNA Polymerase III Abortive And Retractive Initiation; RNA Polymerase III Transcription Initiation From Type 3 Promoter; RNA polymerase II transcribes snRNA genes
Gene Ontology:
Molecular function: protein binding; RNA polymerase II general transcription initiation factor activity; RNA polymerase III general transcription initiation factor activity; sequence-specific DNA binding
Biological process: snRNA transcription by RNA polymerase II; snRNA transcription by RNA polymerase III
Cellular component: nucleolus; nucleoplasm; snRNA-activating protein complex; nucleus
Genetic constraint (gnomAD): Loss-of-function variants: 8 observed, 5.48 expected, observed/expected ratio (o/e) 1.46, 90% interval 0.81 to 1.93. That is too few expected variants to judge how well the gene tolerates losing a copy. Missense variants: 119 observed, 102.33 expected, observed/expected ratio (o/e) 1.16, 90% interval 1 to 1.35. Synonymous variants: 44 observed, 37.49 expected, observed/expected ratio (o/e) 1.17, 90% interval 0.92 to 1.51.
Homologues: Orthologues: chimpanzee SNAPC1 (99% identical), macaque SNAPC1 (98% identical), dog SNAPC1 (89% identical), pig SNAPC1 (87% identical), guinea pig SNAPC1 (85% identical), rat Snapc1 (79% identical), mouse Snapc1 (77% identical), rabbit SNAPC1 (77% identical), tropical clawed frog snapc1 (52% identical), zebrafish snapc1b (38% identical), zebrafish snapc1a (34% identical), Caenorhabditis elegans snpc-1.1 (24% identical), and 4 more.
Diseases named in the same sentence as SNAPC1 in open-access papers:
SNAPC1 is named in the same sentence as 5 diseases in open-access papers, as found by Europe PMC text mining. Sharing a sentence is not in itself a finding about the gene and the disease. The quoted sentences say what the papers report.
allergic asthma (1 paper, 2014). A asthma with a basis in a pathological type I hypersensitivity reaction. "A handful of SNAPC1 targets have already been associated with airway responsiveness and allergic asthma phenotypes." (PMID 25111050, 2014).
tumor (2 papers, 2016 to 2021). "Meanwhile, we found that HIF1A, which is up-regulated in 15 tumor types served as a master TF for the HGLO phenotype in 7 of them, as tumor formation associated gene SNAPC1 was identified as its downstream target in 6 cancers." (PMID 34030708, 2021).
SNAPC1 also shares sentences with these, for which no sentence is quoted: bipolar disorder (1 paper); cancer (1); schizophrenia (1).